UCA1 (urothelial cancer associated 1)
Diseases named in the same sentence as UCA1 in open-access papers (continued):
Sharing a sentence is not in itself a finding about the gene and the disease.
renal carcinoma (9 papers, 2015 to 2023). A carcinoma arising from the epithelium of the renal parenchyma or the renal pelvis. "UCA1 is a powerful tumor biomarker, which highlight its potential clinical utility as a promising diagnostic and therapeutic target of renal cancer." (PMID 31996265, 2020). "Bioinformatics prediction was performed in order to investigate the underlying mechanism of UCA1 in renal cancer in our study, and miR-182-5p were predicted as potential targets." (PMID 31996265, 2020). "Up-regulated UCA1 was positively associated with renal cancer differentiation (P = 0.010), and down-regulated miR-182-5p was positively associated with renal cancer differentiation (P = 0.008) and TNM stage (P = 0.012)." (PMID 31996265, 2020). "Thus, this study demonstrated that UCA1 plays a critical regulatory role in renal cancer cell and UCA1 may serve as a potential diagnostic biomarker and therapeutic target of renal cancer." (PMID 31996265, 2020). "Among all the lncRNA candidates predicted by the BiGAN as being associated with renal cancer, 7 lncRNAs were among the top 10 in the predicted list, (MALAT1 1st, HOTAIR 2nd, PVT1 3rd, NBAT1 4th, UCA1 5th, H19 6th, and MEG3 7th)." (PMID 34193046, 2021). "A recent study reported that highly expressed UCA1 confers renal cancer cells malignant phenotype by acting as a ceRNA." (PMID 34809621, 2021). "The results indicated that UCA1 promotes malignant phenotypes of renal cancer cells via DLL4-dependent manner." (PMID 31996265, 2020). "We found that UCA1 was significantly upregulated in renal cancer cells and UCA1 functioned as a miRNA sponge to positively regulate DLL4 expression through sponging miR-182-5p." (PMID 31996265, 2020). "Meanwhile, we found DLL4 overexpression significantly reversed cell proliferation inhibition of renal cancer cells induced by silencing UCA1." (PMID 31996265, 2020). "We found that decreased UCA1 expression was remarkably decreased compared to the LV-NC group of renal cancer cells in vivo." (PMID 31996265, 2020). "Loss-of-function experiments were performed to investigate the biological roles of UCA1 and miR-182-5p on renal cancer cell proliferation, migration, apoptosis and tumorigenicity." (PMID 31996265, 2020). "Our results showed that the DLL4 specific vector (pcDNA3.1-DLL4) significantly reversed the inhibition of DLL4 expression induced by silencing UCA1 in renal cancer cells." (PMID 31996265, 2020). "In this study, we illustrated that UCA1 promoted tumor cell proliferation or migration and suppressed apoptosis of renal cancer and the mechanism of action." (PMID 31996265, 2020). "The results indicated that UCA1 promoted tumorigenicity of renal cancer cells via upregulating DLL4." (PMID 31996265, 2020). "DLL4 overexpression significantly reversed cell proliferation inhibition and migration of renal cancer cells induced by silencing UCA1, and significantly reversed cell apoptosis promotion of renal cancer cells induced by silencing UCA1." (PMID 31996265, 2020). "The relative expression level of UCA1 and miR-182-5p was detected by using Real-Time qPCR in a total of 88 patients with renal cancer." (PMID 31996265, 2020). "Our study validated that UCA1 and miR-182-5p can be considered as a promising biomarker for the diagnosis of renal cancer." (PMID 31996265, 2020). "Further experiments demonstrated that knockdown of UCA1 inhibited malignant phenotypes and Notch signal path of renal cancer cells, and miR-182-5p was reverse function as UCA1." (PMID 31996265, 2020). "And DLL4 overexpression significantly reversed cell migration of renal cancer cells induced by silencing UCA1." (PMID 31996265, 2020). "This is firstly reported the relation between UCA1 and miR-182-5p as miRNAs sponges in the renal cancers in the world." (PMID 31996265, 2020). "In this research, we evaluated the expression patterns and clinical significances of UCA1 in renal cancer, and furthermore explored its possible function in renal cancer cells." (PMID 31996265, 2020).
renal carcinoma (continued). "The relative expression level of UCA1 was determined by Real-Time qPCR in a total of 88 patients with urothelial renal cancer and in different renal cancer cell lines." (PMID 31996265, 2020). "DLL4 overexpression significantly reversed cell proliferation inhibition and migration of renal cancer cells induced by silencing UCA1, and remarkably reversed cell apoptosis promotion of renal cancer cells induced by silencing UCA1." (PMID 31996265, 2020). "The results showed that UCA1 expression levels were statistically positively correlated with DLL4 expression levels in renal cancer cell lines and knockdown of UCA1 decreased DLL4 expression in renal cancer cells." (PMID 31996265, 2020). "Similarly, as model risk genes, studies have indicated that UCA1 positively regulates DLL4 expression by sponging miR-182-5p, thereby playing an oncogenic role in renal cancer pathogenesis." (PMID 37020128, 2023). "On the other hand, lncRNA urothelial cancer associated 1 (UCA1) positively regulates the expression of Delta-like ligand 4 (DLL4) through sponging miR-182-5p, and subsequently promotes malignant phenotypes of renal cancer." (PMID 34274028, 2021). "We further determined whether UCA1 regulated the expression of DLL4 in renal cancer cells via miR-182-5p-dependent manner." (PMID 31996265, 2020). "Compared with the RPTEC, the UCA1 expression was increased remarkably in both renal cancer cells, 786-O (P < 0.001) and Caki-1 (P = 0.002),and the miR-182-5p expression was significantly decrease in both renal cancer cells, 786-O (P = 0.010) and Caki-1 (P = 0.017)." (PMID 31996265, 2020). "We found knockdown of UCA1 inhibited the tumorigenicity of renal cancer cells in vivo." (PMID 31996265, 2020). "Compared with the 293 T, the UCA1 expression was increased remarkably in both renal cancer cells, 786-O (P < 0.001) and Caki-1 (P < 0.001),and the miR-182-5p expression was significantly decrease in both renal cancer cells, 786-O (P < 0.010) and Caki-1 (P = 0.012)." (PMID 31996265, 2020). "We further determined whether UCA1 promotes cell proliferation and miR-182-5p restrained cell proliferation in renal cancer." (PMID 31996265, 2020). "Furthermore, we found that UCA1 knockdown combined with miR-182-5p over-expression significantly suppressed the malignant behaviors of renal cancer cells." (PMID 31996265, 2020). "In this study, we found that UCA1 was significantly up-regulated in renal cancer." (PMID 31996265, 2020). "This is the first report to illustrate the function of UCA1 and miR-182-5p in renal cancer." (PMID 31996265, 2020). "Moreover, DLL4 overexpression significantly reversed cell apoptosis promotion of renal cancer cells induced by silencing UCA1." (PMID 31996265, 2020). "We further determined whether UCA1 regulated tumorigenicity of renal cancer cells using generation of xenograft." (PMID 31996265, 2020). "In the present study, we showed that UCA1 was involved in the progression of renal cancer." (PMID 31996265, 2020). "Meanwhile, we found knockdown of UCA1 decreased DLL4 expression of renal cancer cells in vivo." (PMID 31996265, 2020). "However, the molecular mechanism of UCA1 in renal cancer is still needed to further explore." (PMID 31996265, 2020). "Together, our results suggest that UCA1 is a powerful tumor biomarker, and UCA1-miR-182-5p-DLL4 axis is involved in proliferation, migration, apoptosis and progression of renal cancer, which highlight its potential clinical utility as a promising diagnostic and therapeutic target of renal cancer." (PMID 31996265, 2020). "Our study reveals that UCA1 functions as a miRNA sponge to positively regulate DLL4 expression through sponging miR-182-5p and subsequently promotes the malignant phenotypes of renal cancer cells, thus playing an oncogenic role in renal cancer pathogenesis." (PMID 31996265, 2020).
renal carcinoma (continued). "Cumulatively, our results suggest that UCA1-miR-182-5p-DLL4 axis is involved in proliferation migration, apoptosis and progression of renal cancer." (PMID 31996265, 2020). "We found knockdown of UCA1 increased DLL1, Jag1, Jag2 and Notch1expression and decreased DLL4, NICD and Hes1 expression of renal cancer cells in vivo." (PMID 31996265, 2020). "Knockdown of UCA1 increased DLL1, Jag1, Jag2 and Notch1expression and decreased DLL4, NICD and Hes1 expression in renal cancer cells." (PMID 31996265, 2020). "However, the relation between UCA1 and renal cancer is still unknown and mysterious particularly." (PMID 31996265, 2020). "The expression of UCA1 was remarkably higher in renal cancer tissues and cell lines, and its up-regulation was positively correlated with differentiation and TNM stage in renal cancer." (PMID 31996265, 2020). "UCA1-miR-182-5p-DLL4 axis is involved in proliferation and progression of renal cancer." (PMID 31996265, 2020).
atherosclerosis (8 papers, 2019 to 2024). A disease characterized by the build-up of fatty material and calcium deposition in the arterial wall resulting in partial or complete occlusion of the arterial lumen. "Lnc‐UCA1 has been recently identified as an atherosclerosis‐associated circulating lncRNA, indicating its involvement in cerebro‐cardiovascular diseases." (PMID 34850451, 2022). "The correlations between plasma levels of UCA1 and miR-132 across atherosclerosis and control plasma samples were analyzed." (PMID 37533737, 2023). "UCA1 was accumulated to high amounts in atherosclerosis plasma, while miR-132 was accumulated to low amounts in atherosclerosis plasma (p < 0.05)." (PMID 37533737, 2023). "There are several possible reasons which explain these findings: (a) lnc‐UCA1 promoted VSMC proliferation, which further led to increased plaque formation, thereby eventually resulted in atherosclerosis and elevated CHD risk." (PMID 34850451, 2022). "The crosstalk between UCA1 and miR-132 in atherosclerosis was therefore analyzed in this research." (PMID 37533737, 2023). "We found that UCA1 was increased in atherosclerosis and may upregulate Lrrfip1 by sponging miR-132 to promote the proliferation of VSMCs." (PMID 37533737, 2023). "In conclusion, UCA1 is upregulated in atherosclerosis and it may sponge miR-132 to upregulate Lrrfip1, thereby promoting the proliferation of VSMCs." (PMID 37533737, 2023). "This research studied the role of lncRNA UCA1 in atherosclerosis." (PMID 37533737, 2023). "UCA1 was upregulated and miR-132 was decreased in atherosclerosis plasma." (PMID 37533737, 2023). "Therefore, UCA1 is downregulated in atherosclerosis and may regulate miR-132/Lrrfip1 axis to promote VSMC proliferation." (PMID 37533737, 2023). "However, it is unclear whether UCA1-regulated miR-132 participates in atherosclerosis." (PMID 37533737, 2023). "It was also reported that lncRNA UCA1 acts as an endogenous sponge of miR-26a and downregulates miR-26a expression levels, and thereby relieving the inhibition of its target gene PTEN and alleviates VSMCs proliferation against atherosclerosis." (PMID 31695578, 2019). "In addition, although UCA1 and miR-132 showed opposite expression patterns in atherosclerosis, they are not significantly correlated with each other across plasma samples." (PMID 37533737, 2023).
breast tumor (7 papers, 2015 to 2024). "Left breast tumors in MBC patients were significantly associated with UCA1 and SPRY4-IT1 down-regulation (P = 0.025 and P = 0.027, respectively)." (PMID 36376369, 2022). "The UCA1 level was positively associated with PTP1B expression in breast tumor tissues." (PMID 31695578, 2019). "The in vivo tumorigenicity assay showed that UCA1 could promote the growth of breast tumor cells." (PMID 31695578, 2019). "In this study, we first evaluated the correlation between UCA1 level and PTP1B expression in breast tissues, which showed the expression of PTP1B were much higher in the breast tumor tissues than in the peritumor normal tissues." (PMID 31695578, 2019). "In breast tumor tissues PTP1B is highly expressed and the expression is positively correlated to UCA1 level." (PMID 31695578, 2019). "It was found that UCA1 was mainly localized in cytoplasm which could interact with phosphorylated heterogeneous nuclear ribonucleoprotein I (hnRNP I) by RIP assay, thereby promoting breast tumor growth by competitive suppression of p27 protein level." (PMID 25760077, 2015).
cardiac hypertrophy (7 papers, 2019 to 2025). "LncRNA UCA1 was able to promote the progression of cardiac hypertrophy, a condition associated with a series of cardiovascular diseases, including heart failure." (PMID 37506155, 2023). "Additionally, lncRNA UCA1 (Long non-coding RNA urothelial carcinoma-associated 1) has been shown to promote the progression of cardiac hypertrophy, a condition commonly associated with various cardiovascular diseases such as heart failure." (PMID 38250803, 2023). "miR-184 can regulate cardiac hypertrophy by targeting Urothelial cancer associated 1 (UCA1)." (PMID 32823859, 2020). "Rescue assays indicated that UCA1 promoted the progression of cardiac hypertrophy through competitively binding with miR-184 to enhance the expression of HOXA9." (PMID 38250803, 2023). "LncRNA UCA1 regulates cardiac hypertrophy via the UCA1/miR-184/HOXA9 axis." (PMID 34604357, 2021). "Likewise, lncRNA UCA1 has been reported to promote the development of cardiac hypertrophy by binding miR-184." (PMID 33173535, 2020).
endometriosis (7 papers, 2020 to 2025). The growth of functional endometrial tissue in anatomic sites outside the uterine body. "Recent literature data suggest that the following lncRNAs are associated with endometriosis: UCA1, MALAT1, TC0101441, and H19." (PMID 36232884, 2022). "Although our data indicated the involvement of UCA1 genetic variants in endometriosis development and the associated infertility, limitations in this study should be addressed here." (PMID 35901079, 2022). "Our study therefore reveals a novel role of UCA1 in endometriosis development and the associated infertility through regulating genes involved in fatty acid metabolism and lipogenesis." (PMID 35901079, 2022). "Gene network analyses revealed fatty acid metabolism and mitochondria beta-oxidation as the major pathways associated with altered UCA1 expression in endometriosis patients." (PMID 35901079, 2022). "In this study, we discovered the involvement of novel haplotypes of UCA1 gene in endometriosis development and the associated clinical outcomes, including long-term pain and infertility." (PMID 35901079, 2022). "The participation of genetic variants of UCA1 in the development of endometriosis and related infertility is indicated." (PMID 36232884, 2022). "Our data indicated three risk genetic haplotypes in UCA1 which can stabilize the RNA structure and increase the susceptibility of endometriosis." (PMID 35901079, 2022). "The lncRNA urothelial cancer-associated 1 (UCA1) is another possible diagnostic biomarker for endometriosis." (PMID 34638965, 2021). "As endometriosis shares several similar phenotypes with cancer including uncontrolled cell proliferation and long-term inflammation, this study reported a novel mechanism in endometriosis development by upregulating UCA1 through stabilizing RNA structures of the risk haplotype variants." (PMID 35901079, 2022). "Allelic and genotypic distributions of selected SNPs in this case-control study were analyzed, and our data indicated that genetic variation of A to G at rs113579010 in UCA1 showed a tendency to increase the risk to develop endometriosis (OR = 1.718; 95% CI: 1.101–2.674)." (PMID 35901079, 2022). "In our study, we also found that endometriosis patients with higher UCA1 were more susceptible to being infertile, part of the reason may be due to unhealthy conditions of the oocyte." (PMID 35901079, 2022). "Significantly, patients with haplotypes of two allelic variants in UCA1 showed stronger correlations with endometriosis development as compared to the controls, suggesting more functional impacts generated by two-locus combinations than one single SNP on endometriosis development." (PMID 35901079, 2022). "Our study thus provides evidence to highlight functional/epigenetic roles of UCA1 in endometriosis development via regulating fatty acid metabolism in women." (PMID 35901079, 2022). "Transcriptome analysis by using dataset from GSE120103 confirmed increased levels of UCA1 in patients with endometriosis." (PMID 35901079, 2022). "Among the SNPs tested in UCA1, allelic types of SNPs at rs113579010, rs73003273 and rs73005445 show lesser risks of endometriosis development (p < 0.100), we therefore analyzed two-locus haplotypes of genetic combinations among these three SNPs." (PMID 35901079, 2022). "In this study, we investigated the possible impacts of genetic variations in these ovary-related lncRNAs, PTENP1, GAS5 and UCA1, on endometriosis." (PMID 35901079, 2022). "In our study, we presented an analysis of the expression of UCA1, MALAT1, TC0101441, and H19lncRNAs in endometriosis patients compared to controls, to possibly correlate these lncRNAs with the risk of endometriosis." (PMID 36232884, 2022). "The study aimed to analyze the expression of four long non-coding RNA (lncRNA) genes, UCA1, MALAT1, TC0101441, and H19, in the context of the risk of developing endometriosis." (PMID 36232884, 2022).